MIF (macrophage migration inhibitory factor)
Diseases named in the same sentence as MIF in open-access papers (continued):
Sharing a sentence is not in itself a finding about the gene and the disease.
multiple myeloma (24 papers, 2017 to 2026). "In summary, the CellChat communication pattern analysis identified the MIF signal pathway as an important signaling mechanism associated with the C0 IGLL5+ Myeloma Cells subgroup and the CLEC signal pathway as a significant pathway corresponding to T_NK cells." (PMID 39281682, 2024). "Taken together, the analysis of the MIF and CLEC signaling pathways reinforced the importance of the C0 IGLL5+ Myeloma Cells subgroup and its association with the MIF pathway, as well as the relevance of the CLEC pathway to T_NK cells." (PMID 39281682, 2024). "Interestingly, we discovered that a subset of C0 IGLC3+ myeloma cells is associated with the MIF signaling pathway, indicating its significance in the signaling network of this subpopulation." (PMID 40406148, 2025). "Notably, the MIF (Macrophage Migration Inhibitory Factor) signal pathway was found to be associated with the C0 IGLL5+ Myeloma Cells subgroup, indicating its importance in the signaling network of this subgroup." (PMID 39281682, 2024). "Using multiple myeloma as an exemplar, comBOs recapitulate niche remodeling and identify macrophage inhibitory factor (MIF) signaling as a disease driver." (PMID 41734765, 2026). "MIF inhibition reduces inflammation and myeloma proliferation, highlighting its therapeutic potential." (PMID 41734765, 2026). "First, the study was carried out based on the MIF signaling network, and the results showed that all four myeloma cell subpopulations were more active." (PMID 40406148, 2025). "These myeloma cells’ biological activities and functions were probably significantly influenced by the MIF pathway." (PMID 40406148, 2025). "To further analyze the MIF signaling pathway, we categorized all nine identified cell types in myeloma as potential MIF source cells." (PMID 39281682, 2024). "These analyses highlighted the complex and multifaceted nature of the MIF signaling pathway in multiple myeloma." (PMID 39281682, 2024). "The stratification plots demonstrated the unique targeting capabilities of C0 IGLL5+ Myeloma Cells and emphasized their role in the MIF-mediated communication network." (PMID 39281682, 2024). "The results indicated that the C0 IGLL5+ Myeloma Cells subgroup had the largest number and the highest centrality score within the MIF signaling pathway." (PMID 39281682, 2024). "CellChat analysis revealed coordinated interactions between the C0 IGLL5+ Myeloma Cells subgroup and other cell types, with the MIF and CLEC signaling pathways identified as important pathways associated with this subgroup." (PMID 39281682, 2024). "The importance of the MIF signaling pathway was underscored by these results, especially within the C0 subgroup of myeloma cells." (PMID 39281682, 2024). "The findings from the analysis of the MIF signaling pathway further supported the strong correlation between the C0 IGLL5+ Myeloma Cells subgroup and this pathway." (PMID 39281682, 2024). "The secretion of C-C motif chemokine ligand 5 (CCL5) and macrophage migration inhibitory factor (MIF) by myeloma cells is a prerequisite for inducing MDSCs in MM." (PMID 36978204, 2023). "Macrophage migration inhibitory factor (MIF) has been shown to promote disease progression directly in many malignancies, including multiple myeloma (MM)." (PMID 37158921, 2023). "MIF (Macrophage Migration Inhibitory Factor) has been shown to accelerates the development of the disease in multiple myeloma." (PMID 37065484, 2023). "The immunomodulatory drugs LEN and pomalidomide reduce CCL5 and macrophage migration inhibitory factor (MIF) expression in myeloma cells, thereby suppressing the generation of MDSCs." (PMID 35854339, 2022). "In multiple myeloma patients, MIF promoted bone marrow stromal cells to secret the cytokines IL-6 and IL-8, which associated with poor prognosis." (PMID 36387901, 2022).
multiple myeloma (continued). "In human myeloma, knocking out MIF is able to overcome resistance to proteasome inhibitors, and MIF has been identified as a biomarker and therapeutic target." (PMID 35060345, 2022). "The approval of milatuzumab, a humanized CD74-targeting antibody in human multiple myeloma and non-Hodgkin lymphoma, and ongoing development of antibodies that target MIF provide candidates to test for therapeutic effects on PNs." (PMID 36134665, 2022). "Macrophage migration inhibitory factor (MIF) has been shown to promote disease progression in many malignancies, including multiple myeloma (MM)." (PMID 34268123, 2021). "We previously reported that MIF regulates MM bone marrow homing and knockdown of MIF favors the extramedullary myeloma formation in mice." (PMID 34268123, 2021). "Here, based on MIF immunostaining of myeloma cells in paired intramedullary and extramedullary biopsies from 17 patients, we found lower MIF intensity in extramedullary MM (EMM) versus intramedullary MM (IMM)." (PMID 34268123, 2021). "In addition, a recent study presenting resistance mechanisms of BCMA CAR T-cell therapy in multiple myeloma, revealed MIF as one of the major immunosuppressive signaling mediators." (PMID 39908652, 2025). "Notably, the myeloma cell subgroup C0 IGLL5+ Myeloma Cells exhibited high expression of genes related to the MIF pathway." (PMID 39281682, 2024). "Also consistent with a paracrine function for tumor-derived MIF, M-MDSC differentiation is induced by human pediatric rhabdomyosarcoma and multiple myeloma cell lines in a MIF-dependent manner and that MIF induces the recruitment and accumulation of M-MDSCs into bladder cancer lesions." (PMID 33324425, 2020). "Milatuzumab, the first anti-CD74 antibody that has entered into clinical tests, is currently being studied for the treatment of non Hodgkin lymphomas, chronic lymphocytic leukemia, and multiple myeloma and could be potentially tested in MIF/CD74 positive CRC-pc." (PMID 28114961, 2017). "MIF interacts with CD74 and CXCR4 on myeloma cells to promote their proliferation, survival, and immune evasion, and also supports the inflammatory environment in the bone marrow to promote tumor progression and immune suppression." (PMID 40406148, 2025). "The MIF signaling pathway was probably important in the biological processes and functions of the C0 IGLL5+ Myeloma Cells subgroup." (PMID 39281682, 2024). "The analysis of the MIF and CLEC signaling pathways reinforced the relevance of the C0 IGLL5+ Myeloma Cells subgroup and provided insights into cell-cell interactions and immune regulation in multiple myeloma." (PMID 39281682, 2024). "Through clarifying the roles of MIF and CLEC signaling pathways and their connections to distinct cell groups, we enhanced our comprehension of the molecular processes involved in multiple myeloma." (PMID 39281682, 2024). "In our cellular interaction analysis, myeloma cells displayed an upregulation of inflammatory cytokines (e.g., CCL3, GRN, AREG, and MIF) that target receptors primarily expressed in the myeloid and dendritic cell compartment." (PMID 34845188, 2021). "In myeloma cells, ALCAM is a downstream response protein to migration inhibitory factor (MIF) and an important factor in the interaction between myeloma cells and bone marrow stromal cells." (PMID 34680335, 2021). "Therapeutic monoclonal antibodies targeting MIF (imalumab) and its canonical receptor CD74 (milatuzumab) have been developed, with milatuzumab achieving orphan drug designation from the FDA for the treatment of multiple myeloma." (PMID 41122966, 2025). "Moreover, previous studies had reported that MM cells express high levels of MIF, which aligned with the current findings and reinforces the significance of the C0 IGLL5+ Myeloma Cells subgroup in this study." (PMID 39281682, 2024).
multiple myeloma (continued). "In Multiple Myeloma (MM), the expression of CD84 in MM cells was found to be decreased, and these cells could secret Macrophage Migration Inhibitory Factor (MIF), which was able to promote CD84 expression." (PMID 39013845, 2024). "Interestingly, we observed that MIF played a significant role in both incoming and outgoing signaling of C0 IGLL5+ Myeloma cells." (PMID 39281682, 2024).
psoriasis (23 papers, 2013 to 2025). An autoimmune condition characterized by red, well-delineated plaques with silvery scales that are usually on the extensor surfaces and scalp. "The MIF gene polymorphism and increased MIF protein concentration are associated with the incidence of ulcerative colitis, psoriasis, and tuberculosis." (PMID 36186991, 2022). "Macrophage migration inhibitory factor (MIF) is another cytokine implicated in the pathogenesis of psoriasis." (PMID 35837394, 2022). "Nevertheless, we studied circulating levels of MIF and found a relationship between this allele and higher serum levels of MIF in patients with psoriasis." (PMID 34533238, 2021). "We have addressed the pathogenic significance of MIF in psoriasis using the IIPD and the IL-23-induced dermatitis mouse models." (PMID 30333830, 2018). "Polymorphism of MIF on the −173 position has been reported in several inflammatory diseases, including ulcerative colitis (UC), psoriasis and tuberculosis (TB)." (PMID 28578664, 2017). "MIF gene encodes a lymphokine involved in cell-mediated immunity, immune regulation, and incorporated in various immune skin disorders like bullous pemphigoid, psoriasis, vitiligo, systemic sclerosis, lupus erythematosus, and atopic dermatitis." (PMID 40445486, 2025). "MIF polymorphisms have been associated with an increased risk of psoriasis." (PMID 35837394, 2022). "Expression levels of MIF are also significantly elevated in the skin and serum of psoriasis patients, but the pathogenic significance of MIF in psoriasis is unknown." (PMID 30333830, 2018). "Furthermore, polymorphisms in the promoter of the MIF gene are associated with a higher susceptibility to psoriasis." (PMID 30333830, 2018). "Moreover, elevated MIF serum levels were associated with severe clinical symptoms of psoriasis." (PMID 40445486, 2025). "MIF induces the production and secretion of IL‐17A and promotes the differentiation of Th17 cells, which are major contributors to inflammation in psoriasis." (PMID 41249858, 2025). "Serum MIF levels were higher in psoriasis patients than in healthy controls, and the serum MIF level was positively correlated with the clinical severity score." (PMID 35837394, 2022). "Transcriptomic data revealed strong increased mRNA levels of PARP1, AIFM1, and MIF in psoriasis lesional skin." (PMID 34748530, 2021). "All of these would support the suggestions of MIF as a target for future therapies in psoriasis or other skin diseases." (PMID 34533238, 2021). "Collectively, our results lend support to a possible disease-promoting role of MIF in psoriasis, which should be further investigated." (PMID 30333830, 2018). "With the IL-23/IL-17 pathway most critical in both IIPD and human psoriasis, we set out to investigate the role of MIF specifically in this pathway." (PMID 30333830, 2018). "We have therefore addressed the role of MIF in two mouse models of psoriasis, namely in the imiquimod-induced psoriasiform dermatitis (IIPD) and the IL-23-induced dermatitis model." (PMID 30333830, 2018). "MIF has been implicated in the pathogenesis of plaque psoriasis by observations that serum levels are elevated in psoriasis patients and that their PBMCs spontaneously release higher amounts of MIF than those of healthy controls." (PMID 30333830, 2018). "Earlier studies have found that circulating MIF levels are elevated in ulcerative colitis (UC), psoriasis and tuberculosis (TB)." (PMID 28578664, 2017). "The MIF levels in patients with psoriasis were also found to be significantly higher than those in controls." (PMID 25821795, 2015). "Further studies are needed to clarify the involvement of MIF in the pathogenesis of psoriasis." (PMID 35837394, 2022). "However, in contrast to elevated serum MIF in psoriasis patients, MIF-positive cells were significantly decreased in the lesional psoriatic epidermis." (PMID 35837394, 2022).
psoriasis (continued). "The skin and serum of psoriatic patients express increased levels of MIF, but its pathogenic function in psoriasis is still not clear." (PMID 34533238, 2021). "Interestingly, the pattern of modulation of MIF in DLE appears to be strikingly different for psoriasis." (PMID 33401503, 2021). "Through this function in host defense, MIF may promote the pathogenesis of psoriasis and the emergence of psoriatic lesions, which often emerge in response to exogenous microbial stimuli." (PMID 30333830, 2018). "Therefore, we have addressed the significance of MIF in the pathogenesis of psoriasis using two mouse models, the imiquimod-induced psoriasiform dermatitis (IIPD) and the IL-23-induced dermatitis model." (PMID 30333830, 2018). "Despite this well-defined increased activity of MIF in psoriasis, the pathogenic role of MIF in this disease has not been investigated." (PMID 30333830, 2018). "Interestingly, the role of MIF inducing the recruitment of IFN-γ-producing NKT cells in a murine model of psoriasis has been recently demonstrated." (PMID 27057101, 2016). "In this study, TAN significantly inhibited the levels of iNOS, TNFα, IL-6, IL-10, IL-20, MIF, and MCP-1 in psoriasis mice, which had a wide range of inflammatory inhibitory effects." (PMID 38832986, 2024). "Thus, MIF may be involved in the recruitment of macrophages in psoriasis patients." (PMID 35837394, 2022). "In psoriasis, Langerhans cells were predominantly and strongly involved via COLLAGEN and LAMININ pathways, while a variety of cell types participated in the APP pathway, primarily featuring T-cells in the MIF pathway." (PMID 38289616, 2024). "We identified APP pathway-related ligand receptor proteins, including APP and CD74 (CD74 Antigen), with upregulated protein expression in pathological tissue sections of psoriatic skin (Psoriasis/Normal skin Ratio in CD74 protein: 1.202; Psoriasis/Normal skin Ratio in MIF protein: 1.239)." (PMID 38289616, 2024). "On the other hand, if we assume that MIF has a key role in the severity of psoriasis, the lack of correlation in our study could be explained by the low PASI score of our patients." (PMID 34533238, 2021).
coronary artery disease (22 papers, 2010 to 2025). "The MONICA/KORA Augsburg study concluded that female carriers of the MIF -173C polymorphism were at higher risk of coronary heart disease." (PMID 38476376, 2024). "Of note, a G/C single-nucleotide polymorphism (rs755622) at position −173 of human MIF gene is associated to a higher susceptibility to develop coronary diseases and cancers." (PMID 35115654, 2022). "Genetic variation of macrophage migration inhibitory factor (MIF) gene has been linked to coronary artery disease." (PMID 35046995, 2021). "The longer CATT7 repeat further has been associated with higher serum MIF levels in various patient cohorts, including those with coronary artery disease." (PMID 32932965, 2020). "The area under the ROC curve was 0.980, suggesting that the diagnostic value of MIF for coronary heart disease is high." (PMID 25821795, 2015). "This study explored the association of 173G/C polymorphism of the MIF gene with coronary heart disease (CHD)." (PMID 25821795, 2015). "Various studies from all over the world have been conducted to know the genetic polymorphism in coronary artery disease; this study, however, mainly includes the Vijayapura Karnataka population and has attempted to screen the presence of MIF polymorphism in these patients." (PMID 39439602, 2024). "On the other hand, the impact of MIF and APOA5 on HF are likely mediated by the risk of coronary artery disease, a leading cause of HF." (PMID 35964012, 2022). "In fact, it was reported that MIF knock-out mice or the administration of an anti-MIF antibody to mice showed a suppressing effect on ischemic heart disease." (PMID 35335938, 2022). "Multivariable MR showed that association of BAG3, MIF and APOA5 with HF were mediated by the blood pressure and coronary artery disease." (PMID 35964012, 2022). "BAG3 is significantly and negatively associated with systolic and diastolic blood pressure, whereas MIF and APOA5 are associated with coronary artery disease." (PMID 35964012, 2022). "However, some proteins such as BAG3, MIF and APOA5 show concordant associations between HF, the blood pressure (BAG3) and coronary artery disease (MIF and APOA5)." (PMID 35964012, 2022). "Second, numerous factors can influence the occurrence and development of coronary heart disease, and we did not consider other polymorphisms in MIF, such as -794CATT5–8, or in other related genes." (PMID 32560699, 2020). "In this study, we investigate whether MIF could rejuvenate aged MSCs and enhance their function, so they could be applied to the treatment of ischemic heart diseases." (PMID 25896286, 2015). "In the process of myocardial remodeling, MIF is generally thought to be an important factor in the progression of pathological conditions because its expression is increased and the inflammatory reaction is promoted in heart failure such as ischemic heart disease." (PMID 35335938, 2022). "Evaluation of baseline characteristics revealed that patients suffering from coronary artery disease (CAD) showed significant lower MIF levels after ICU admission in univariate analysis (P = 0.0395); however, this effect could not be confirmed in the multivariable model (P = 0.2790)." (PMID 29120365, 2017). "From a clinical perspective, the protective effect of exogenous MIF during ischemic heart diseases may not only be due to energy modulation, protection of cardiomyocytes and regulation of cardioprotective proteins, but also due to their rejuvenative effect on circulating stem cells." (PMID 25896286, 2015). "Hence, strategies that can facilitate regaining of endogenous MIF level and activity might provide an additive effect while using MSCs to treat ischemic heart diseases, especially in aged patients." (PMID 25896286, 2015). "An increased expression of MIF and its ligand CD74 was also detected in the diabetic patients with coronary artery disease." (PMID 25661015, 2015).
coronary artery disease (continued). "Notably, human fibroblasts with a low-expression MIF allele have diminished MIF release and AMPK activation during hypoxia, suggesting that the predetermination of MIF genotype might predict risk in patients with coronary artery disease." (PMID 20169173, 2010). "Macrophage migration inhibitory factor (MIF) is an essential mediator of atherosclerotic plaque progression and instability leading to intracoronary thrombosis, therefore contributing to coronary artery disease (CAD)." (PMID 33850223, 2021).